BRCA1 (BRCA1 DNA repair associated)
Diseases named in the same sentence as BRCA1 in open-access papers (continued):
Sharing a sentence is not in itself a finding about the gene and the disease.
breast cancer (continued). "This large cohort study of women with breast cancer who underwent germline testing provided information about BRCA1 and BRCA2 in a population enriched for Hispanic women and reported the prevalence of P/LP variants when universal BRCA1 and BRCA2 testing is offered to women with breast cancer." (PMID 40952741, 2025). "BRCA1 and BRCA2 mutations contribute to approximately 10–15% of all breast cancers." (PMID 40941615, 2025). "The lower breast cancer-specific survival rate for BRCA2 compared with BRCA1, which is considered to have a poorer prognosis, may provide a glimpse into the proper long-term prognosis of BRCA2 but needs further investigation." (PMID 41083355, 2025). "The expression of thyroid hormone receptor beta (TRβ) was significantly higher in breast cancer associated with BRCA1 compared to sporadic breast cancer, the latter not being linked to BRCA1 (p = 0.001)." (PMID 40361383, 2025). "For example, deletion of BRCA1 (HGNC: 1100) exon 86 and CHEK2 (HGNC: 16627) exons 9-109 have been associated with breast cancer predisposition (OMIM 604370, 609265), and BRCA1 full-gene deletion has been described in 2 Spanish families with hereditary breast and ovarian cancer." (PMID 41210374, 2025). "Prior studies have focused on BRCA1/2 PV carriers and generally shown little or no increase in breast cancer risk associated with alcohol consumption, tobacco use, or obesity." (PMID 40298171, 2025). "The use of lincRNAs in the pathophysiology of BRCA1-associated breast cancer remains limited, primarily due to the lack of functional validations in the existing lincRNA databases." (PMID 39997609, 2025). "However, other lincRNAs identified, such as lincRNA-BC7, remain uncharacterized concerning their role in breast cancer and BRCA1." (PMID 39997609, 2025). "MYC amplification is frequent in breast cancers that have inactive BRCA1." (PMID 39885374, 2025). "In addition, down-regulated BRCA1 expression in breast cancer cells was observed following AZD4573 treatment in this study." (PMID 40713627, 2025). "For ovarian cancer (in both TCGA-OV and HD-OV), breast cancer (in TCGA-BRCA), and the remaining cancer types (TCGA-PANCAN*), biallelic (BA) mutations of BRCA1/2 (class H1a) were associated with significantly lower fdeam compared with tumors without alterations in the HR-genes (class H3)." (PMID 40730886, 2025). "Metabolomics was used to show bioenergetics changes in BRCA1-expressing breast cancer cells." (PMID 40863152, 2025). "Hispanic women with breast cancer were 2.58 times as likely as non-Hispanic women to carry a P/LP germline variant in BRCA1 than BRCA2 variants (odds ratio [OR], 2.58 [95% CI, 1.16-5.88]; P = .02)." (PMID 40952741, 2025). "PARP inhibitors such as olaparib and talazoparib have been approved for unresectable/recurrent breast cancer with germline BRCA1 or BRCA2 (BRCA1/2) mutations and without HER2 expression." (PMID 40861716, 2025). "MHT after premenopausal salpingo-oophorectomy in BRCA1/2 PV carriers has generally not been associated with higher breast cancer risk." (PMID 40298171, 2025). "A recent study further showed that RAPTA-T causes much more cellular BRCA1 damage in triple-negative BRCA1-defective HCC1937 breast cancer cells than in sporadic BRCA1 wide-type MCF-7 breast cancer cells, leading to a reduction in both BRCA1 mRNA expression and the BRCA1 protein in both cell lines." (PMID 41226649, 2025).
breast cancer (continued). "Together, the data suggest that all three MDAMB436 OR clones have acquired similar CC50 values to those seen in BRCA WT breast cancer cell lines by reestablishing BRCA1 expression and HDR functionality and with that eliminating the synthetic lethal effect that its absence has with PARP inhibition." (PMID 40669753, 2025). "Additionally, the presence of a BRCA1 or BRCA2 mutation, which indicates a high risk of developing breast cancer, has been linked to greater psychological distress and diminished quality of life, even in the absence of an active cancer diagnosis." (PMID 41192943, 2025). "Female carriers of pathogenic variants in BRCA1 or BRCA2—both high-penetrance genes associated with hereditary breast and ovarian cancer (HBOC)—face a lifetime risk of 50%‐80% for breast cancer, a 60% risk for contralateral breast cancer, and up to 40% for ovarian cancer." (PMID 40471748, 2025). "For BRCA1 and BRCA2 carriers, few studies with small sample sizes, high heterogeneity, low quality, and varied measurements of exposure have assessed the impact of modifiable risk factors on breast cancer risk." (PMID 39858629, 2025). "These rates are intermediate between those reported in BRCA1 carriers (57% high grade, 85% TN) and BRCA2 carriers (56% high grade, 23% TN), suggesting differences in tumor biology between PHTS and BRCA-associated breast cancers." (PMID 40075703, 2025). "Moreover, through a MetaCore functional enrichment analysis, GNPDA1 and SLC25A16 were associated with the BRCA1, BRCA2, and pro-oncogenic actions of the androgen receptor in breast cancer." (PMID 40278313, 2025). "Moreover, we extended this investigation to include BRCA1-mutated tumors from both TNBC and HER2– breast cancer patients who exhibited PARPi resistance in clinical settings." (PMID 40460005, 2025). "Although a survival benefit has been demonstrated for carriers of P/LP variants in BRCA1 undergoing either IBS or RRM, with RRM being associated with significantly lower breast cancer-specific mortality, the choice between IBS or RRM is based on the carrier’s preferences and beliefs." (PMID 40445415, 2025). "The dysregulated expression of HOTAIR in BRCA1 has been observed in breast cancer." (PMID 39997609, 2025). "Similarly, BRCA1 expression in certain breast cancers is downregulated by a switch to a longer 5′UTR, which introduces secondary structures or upstream regulatory elements that modulate expression levels." (PMID 40282372, 2025). "Heritable breast cancer (BC) is influenced by well-known high-penetrance genes such as BRCA1, BRCA2, PALB2, and CHEK2, but the contribution of many moderate- and low-penetrance genes remains unclear." (PMID 41463216, 2025). "Expanding access to genetic testing and availability of validated breast cancer (BC) risk prediction models are increasingly identifying women at elevated BC risk who do not carry high-penetrance BRCA1/BRCA2/PALB2 pathogenic variants." (PMID 40705362, 2025). "A 72‐year‐old patient who first presented with bilateral breast carcinoma with negative BRCA1/2 mutational testing was treated with hormonal therapy until she recurred with an abnormal mammogram 13 years later." (PMID 41473825, 2025). "An expanding database of evidence suggests that miR-155’s activity in breast cancer (BC) is linked to BRCA1, as the absence of functional BRCA1 has been shown to elevate miR-155 expression levels, and conversely, by direct targeting of the miR-155 promoter." (PMID 40699776, 2025). "Mutations in the BRCA1 and BRCA2 genes are a risk factor for breast cancer in men and may be a consequence of exposure to XEs." (PMID 39596429, 2024). "Mutations of the BRCA1 and BRCA2 genes lead to an increased risk of breast cancer." (PMID 38339129, 2024).
breast cancer (continued). "We previously demonstrated that loss of p18, a cell cycle inhibitor, in mice induces luminal-type mammary tumors, whereas depletion of either Brca1 or Gata3 in p18 null mice leads to basal-like breast cancers (BLBCs) with activation of epithelial-mesenchymal transition (EMT)." (PMID 38627785, 2024). "Background/Objectives: BRCA1 pathogenic variant (PV)-associated breast cancers are most commonly seen in hereditary genetic conditions such as the autosomal-dominant Hereditary Breast and Ovarian Cancer (HBOC) syndrome, and rarely in sporadic breast cancer." (PMID 39682099, 2024). "Low levels of zinc (Zn) in women with the BRCA1 mutation is weakly associated with an increased risk of ovarian cancer, although there was no similar association with breast cancer." (PMID 39275213, 2024). "This analysis showed no significantly increased risk of breast cancer due to HRT after RRSO in BRCA1/2-pV carriers." (PMID 39259360, 2024). "No significant breast cancer risk was found for healthy women, but BRCA1/2 mutation carriers faced increased risks." (PMID 39606555, 2024). "Also, the well-known genes BRCA1 and BRCA2 that predispose to breast cancer are considered to be part of the FANC gene family." (PMID 39051418, 2024). "From our correlation analysis of gene and protein expression we have observed that out of these three MBD proteins only MBD2 gene regulate the BRCA1 gene expression in ER+ & PR+ & Triple negative breast cancer cells, others only have regulation in ER+ & PR+ breast cancer cells." (PMID 38711004, 2024). "We benchmarked GraphTucker against the baseline methods to evaluate its performance in cross-validation experiments across three 10x Genomics Visium datasets including mouse brain sagittal-anterior (MBSA) and sagittal-posterior (MBSP) datasets, and a human breast cancer (BRCA1) dataset." (PMID 38940176, 2024). "Notably, while BRCA1/2 germline variants accounted for 46% (23% in BRCA1 and 23% in BRCA2) of these pathogenic changes, a substantial 54% were found in other breast cancer predisposition genes." (PMID 39590369, 2024). "Pathogenic BRCA1/2 variants have been linked to poorer OS in patients with breast cancer but without significant impact on breast cancer-specific survival." (PMID 39319938, 2024). "BRCA1 is a breast cancer marker prominently expresses in 4T1 cells." (PMID 38796426, 2024). "The data from this study reveals that individuals carrying BRCA1/2 mutations tend to be diagnosed with breast cancer at a younger age compared to those without the mutations." (PMID 38167124, 2024). "Clinical and pathologic characteristics for patients with BRCA1 and BRCA2 were compared, and estimates of overall survival, bilateral mastectomy-free survival, distant disease-free survival, risk of ipsilateral breast cancer, and risk of contralateral cancer were computed." (PMID 38916888, 2024). "Her group compared BRCA1/2 mutation carriers who chose RRBM versus those who preserved their breasts and concluded that, in women with a BRCA1 or BRCA2 pathogenic variant, RRBM reduced the risk of breast cancer (HR 0.20)." (PMID 38717180, 2024). "The primary objective of this study was to determine the prevalence of GPVs in BRCA1, BRCA2, and PALB2 (B1B2P2) as well as in other breast cancer susceptibility genes (BCSGs) within a racially and ethnically diverse cohort of women with newly diagnosed breast cancer." (PMID 39226054, 2024). "GR dysregulation in BRCA1 mutation carriers with breast cancer reduces the phosphorylation of GR at the Ser-211 position compared with women without breast cancer." (PMID 39201170, 2024). "A large prospective cohort study published in 2020, including 2272 BRCA1 and 1605 BRCA2 pathogenic variant carriers, did not observe a protective effect of RRBSO regarding breast cancer in BRCA1 mutation carriers." (PMID 38892081, 2024).
breast cancer (continued). "Women with BRCA1/2 mutations without a personal history of breast cancer should be advised that HT is an option after risk-reducing bilateral salpingo-oophorectomy." (PMID 39660328, 2024). "Nonetheless, a study of the remaining lifetime risk for the subset of women who were older than 65 years in the population-based CARRIERS project indicated that BRCA1, BRCA2, and PALB2 PVs were associated with enough breast cancer risk to warrant high-risk screening." (PMID 37861889, 2024). "Researchers previously identified breast cancer susceptibility gene 2 (BRCA2) by performing genetic linkage analysis with families affected by early-onset breast cancer who did not carry BRCA1 mutations." (PMID 38773604, 2024). "Moreover, the administration of HRT necessitates a nuanced evaluation of its potential benefits and risks, particularly for those with a breast cancer history, highlighting the significance of individualized care in BRCA1/2 carriers." (PMID 39201170, 2024). "The Prospective Outcomes in Sporadic versus Hereditary breast cancer (POSH) study reported the 10-year overall survival of 558 TNBC patients with or without BRCA1/2 mutations." (PMID 38689097, 2024). "Furthermore, discovering pathogenic variants in BRCA1 DNA repair associated (BRCA1) and BRCA2 genes has been pivotal to our understanding of both hereditary and sporadic breast cancers." (PMID 39484719, 2024). "Furthermore, the rate of BRCA1/2 carriers (21.0%) in our study population was equal to that reported in patients with familial breast cancer (18.1%)." (PMID 38878125, 2024). "Pathogenic and likely pathogenic germline variants in the BRCA1 and BRCA2 genes play a pivotal role in breast cancer development and progression and can determine the optimal risk-reducing strategies and personalized case management for the carriers of such variants." (PMID 39796670, 2024). "Similarly, the vast majority of patients benefiting from genomically-tailored therapy in a recently reported breast cancer trial either had a PIK3CA mutation and received alpelisib, or had BRCA1/2 or similar alterations and received olaparib." (PMID 38612902, 2024). "An increase in breast cancer risk due to hormonal contraception in BRCA1/2-pV carriers cannot be ruled out based on the current data." (PMID 39259360, 2024). "There are no studies on risk of HRT after RRSO on breast cancer recurrence in premenopausal BRCA1/2-pV carriers or of carriers of pV in other breast and/or ovarian cancer genes or genes of the Lynch-syndrome." (PMID 39259360, 2024). "Compared to non-carriers, the average age at diagnosis of BRCA1/2 mutation carriers was younger, and more individuals under 40 were diagnosed with breast cancer, which is consistent with the results of previous reports." (PMID 38167124, 2024). "Taken together, these results suggest that mutations of USP4 L301R, S315C, and R559W may play a role in the pathogenesis of breast cancer, probably through destabilizing BRCA1." (PMID 38734703, 2024). "It is reported that 55–72% of women who inherit a harmful BRCA1 variant and 45–69% of women who inherit a harmful BRCA2 mutation will develop breast cancer by 70–80 years of age, while the chances of developing breast cancer among the general population at some point in their lives is about 13%." (PMID 38672725, 2024). "Next, analysis of the proportion of pleiotropic variants linked to genes associated with leukocyte telomere length revealed an enrichment in breast cancer caused by pathological variants of BRCA1 and TNBC (32% of variants), followed by luminal A breast cancer (LumA; 16%) and melanoma (12%)." (PMID 38308367, 2024). "A more detailed analysis did note higher response rates for patients with DDR+ breast cancer (55% vs 25% DDR-), BRCA1 mutations (50% vs 23% DDR-), and MUTYH mutations (40% vs 23% DDR-), but none of these subgroups reached statistical significance due to the small sample sizes." (PMID 38348036, 2024).
breast cancer (continued). "This individual had no documented family history of breast cancer, history of hormone treatments, BRCA1, BRCA2, PALB2 or CHEK2 P/LP variants or other explanation on chart review." (PMID 39802765, 2024). "Demographics and cancer-related characteristics of early-stage and advanced breast cancer patients in both pathogenic germline BRCA1/2 mutation (gBRCAm) tested and non-tested patients." (PMID 39319938, 2024). "In addition, both BRCA1 and BRCA2 mutations predispose to a breast cancer lifetime risk of greater than 60%." (PMID 38256099, 2024). "Similar defects in fork recovery were observed in a BRCA1-deficient ovarian cancer cell line, UWB1.289 (UW, for simplicity), and in BRCA1-depleted MDA-MB-231 breast cancer cells upon loss of either RAD18 or UBC13, indicating that the observed phenotype is not cell type specific." (PMID 38943334, 2024). "On the basis of mutated genes in cBioPortal database, which was targeted sequencing of 2509 primary breast tumors with 548 matched normal tissues, a total of 30 genes including BBC driver mutations BRCA1, BRCA2, CHEK2 and other high frequency mutations in breast cancer were represented." (PMID 38800414, 2024). "Additionally, while the genetic basis of BRCA1 PV breast cancer is well-studied, the role of epigenetic mediators in the tumourigenesis of these hereditary breast cancers is also worth exploring." (PMID 39682099, 2024). "Based on its role in stabilizing BRCA1, we speculate that USP4 mutations could exist and be a mechanism for the downregulation of BRCA1 in those breast cancers." (PMID 38734703, 2024). "Among 40 recurrent driver alterations described in breast cancer, only HER2 amplification, germline BRCA1/2 mutations, and PIK3CA mutations were given level 1A evidence as molecular targets whereas NTRK fusions and microsatellite instability (MSI) were ranked as 1C evidence." (PMID 38869741, 2024). "Noticeably, all studies, except for one longitudinal report, analyzed breast cancer risk following HRT in BRCA1 carriers together with no differentiation between BRCA1/2 and BRCA2." (PMID 39201170, 2024). "In addition to BRCA1/2-mutant breast cancer, PARPi is also approved for the treatment of ovarian, pancreatic, and prostate cancer." (PMID 38956205, 2024). "We treated Brca1+/− or Gata3+/− mammary tumor cells with olaparib (OLA), a PARP inhibitor." (PMID 38627785, 2024). "Taken together, our study suggest USP4 is a key regulator of BRCA1 and dysregulation could play an important role in the pathogenesis of breast cancer." (PMID 38734703, 2024). "The impact of somatic BRCA1/2 mutations, which occur later in life and are not inherited, also contributes to breast cancer classification." (PMID 39272660, 2024). "SIRT4 targets H4K16ac and BRCA1 as new key factors in breast cancer cells and breast CSCs." (PMID 38397988, 2024). "Interestingly, the phenotype of BRCA1/2-related breast cancers in men seems more aggressive than in women." (PMID 39314558, 2024). "A total of 409 breast cancer patients were analyzed based on next-generation sequencing results, with 337 categorized as non-carriers and 72 as carriers of BRCA1/2 variants." (PMID 38167124, 2024). "The identification of MBD2 as a negative regulator of BRCA1 expression, along with the functional consequences on cell behavior, adds depth to our understanding of epigenetic and pharmacological interventions in breast cancer." (PMID 38711004, 2024). "The study was performed on 45 FFPE breast cancer tissues obtained from 24 and 21 patients, with and without the germline BRCA1/2 mutation, respectively." (PMID 39080120, 2024).